TG (thyroglobulin)
Diseases named in the same sentence as TG in open-access papers (continued):
Sharing a sentence is not in itself a finding about the gene and the disease.
Hashimoto thyroiditis (continued). "This prospective study evaluated the influence of chronic lymphocytic thyroiditis on the risk of persistence and recurrence of papillary thyroid carcinoma in patients with negative thyroglobulin but elevated antithyroglobulin antibodies after initial therapy." (PMID 28625809, 2018). "One child was diagnosed as having Graves' disease based on a positive result for thyroid stimulating antibody and 3 children were diagnosed as having Hashimoto's thyroiditis based on positive results of anti-thyroglobulin antibody and anti-thyroid peroxidase antibody." (PMID 25762224, 2015). "To date, the ‘gold standard’ model for Hashimoto's thyroiditis, murine experimental autoimmune thyroiditis (EAT), can be induced, in susceptible mice, by immunization with either autologous or heterologous thyroglobulin, in conjunction with complete Freund's adjuvant or with lipopolysaccharide." (PMID 21559421, 2011). "Hashimoto’s thyroiditis (HT), also known as chronic lymphocytic thyroiditis, is a common autoimmune disorder characterized by widespread thyroid enlargement and the presence of high levels of thyroid peroxidase antibodies (TPOAb) and thyroglobulin antibodies (TgAb) in the serum." (PMID 39403393, 2024). "Hashimoto’s thyroiditis (HT) is an autoimmune disruption manifested by immune cell infiltration in thyroid tissue and the production of antibodies against thyroid-specific antigens, such as the thyroid peroxidase antibody (TPOAb) and thyroglobulin antibody (TGAb)." (PMID 38137348, 2023). "As the most common organ-specific autoimmune disorder, Hashimoto’s thyroiditis (HT) is characterized by infiltration of the thyroid gland by inflammatory cells and production of autoantibodies to thyroid-specific antigens such as thyroglobulin (Tg) and thyroid peroxidase (TPO)." (PMID 26761929, 2016). "The search terms included "Hashimoto's thyroiditis", "Hashimoto's disease", "levothyroxine", "L-thyroxine", "anti-TPO", "anti-TG", "anti-thyroid antibodies"." (PMID 42278392, 2026). "The epitopes recognized by these autoantibodies in various thyroglobulin regions appear to differ between SAT and Hashimoto’s thyroiditis (HT)." (PMID 40362412, 2025). "When the immune system incorrectly targets healthy thyroid proteins including thyroglobulin (Tg) and TPO, a condition known as Hashimoto thyroiditis develops." (PMID 39507294, 2024). "Serum TSH, anti-TG, and anti-TPO levels were typically lower in controls and much higher in patients with Hashimoto’s thyroiditis." (PMID 37241088, 2023). "Biochemical evaluation of the patient’s thyroid function showed positive thyroglobulin antibody combined with high TSH and low FT4, suggestive of Hashimoto thyroiditis with subsequent primary hypothyroidism." (PMID 38152125, 2023). "In Hashimoto’s thyroiditis, 200 μg of sodium selenite or selenomethionine per day for 3 and 6 months was found to alleviate auto-TPO Ab and anti-thyroglobulin antibody titers and improve thyroid echogenicity." (PMID 37060084, 2023). "Serum TSH, anti-TG, and anti-TPO levels were typically lower in controls and much higher in individuals with Hashimoto’s thyroiditis." (PMID 37241088, 2023). "In this animal model, DA strain rats are high responders and PVG strain rats are low responders; serum antibody titers to thyroglobulin are elevated in both DA and PVG rats, but lymphocytic thyroiditis occurs only in DA rats." (PMID 36838255, 2023). "Anti-thyroglobulin and anti-TPO antibodies were observed in 23/79 patients (29%), but only one patient presented clinically overt autoimmune hypothyroidism." (PMID 36556267, 2022). "Hashimoto’s disease is diagnosed based on the clinical picture, elevated serum levels of anti-TPO and/or anti-TG antibodies, abnormal serum levels of thyroid hormones, and a characteristic ultrasound image of the thyroid gland." (PMID 35565695, 2022).
Hashimoto thyroiditis (continued). "As expected, anti-TG and anti-TPO auto-antibodies were significantly higher in the group of patients with lymphocytic thyroiditis (Group 1) (p<0.001 for both)." (PMID 35317375, 2021). "The possible mechanism is that thyroid antigens including thyroglobulin (TG) and thyroperoxidase (TPO) are released in the situation of Hashimoto’s thyroiditis." (PMID 33228616, 2020). "Abzymes that break down thyroglobulin and the fluorescently labeled tripeptide Pro-Phe-Arg-MCA are revealed in Hashimoto’s thyroiditis." (PMID 32751323, 2020). "Graves’ disease and Hashimoto’s thyroiditis are representative AITD, and TRAb is the autoantibody for Graves’ disease, while the anti-thyroid peroxidase (TPO) antibody and anti-thyroglobulin antibody are autoantibodies for Hashimoto’s thyroiditis." (PMID 33260824, 2020). "Hashimoto’s disease is usually diagnosed by high TSH and elevated antithyroid peroxidase (anti-TPO) and/or anti thyroglobin (anti-TG) antibodies." (PMID 27200380, 2016). "Another Hashimoto thyroiditis patient's serum with high titers of both anti-TPO and anti-TG antibodies confirmed by radioimmunoassay was employed as positive control in indirect immunofluorescence assay." (PMID 22126669, 2011). "It was found that, in patients without Hashimoto’s thyroiditis, factors such as age, sex, aspect ratio, calcification, unclear margin, serum thyroglobulin, tumor size, multifocality, laterality, and capsule invasion were the risk factors (p < 0.05)." (PMID 40496557, 2025). "This occurrence may be attributed to the release of thyroid antigens, such as thyroglobulin (TG) and thyroperoxidase (TPO), in Hashimoto’s thyroiditis." (PMID 40937419, 2025). "Pro-inflammatory arachidonic acid (AA) derivatives may play a vital role in the development of Hashimoto’s Thyroiditis (HT) and the production of anti-thyroid peroxidase antibodies (ATPO) and anti-thyroglobulin antibodies (ATG)." (PMID 41439954, 2025). "Resolvin D1 may have the greatest potential to positively influence inflammation in inflammatory thyroid disease, Hashimoto’s thyroiditis, as it lowers both anti-TPO and anti-TG antibody levels." (PMID 39519244, 2024). "In individuals with Hashimoto’s thyroiditis, the production of anti-thyroid peroxidase antibodies (anti-TPO antibodies) and anti-thyroglobulin antibodies can lead to attacks on thyroid tissue, affecting thyroid hormone synthesis and causing inflammation and damage." (PMID 37876541, 2023). "Hashimoto’s thyroiditis is T cell mediated rather than antibody mediated and the clinically measured thyroid antibodies to thyroglobulin and thyroid peroxidase are secondary to the tissue damage (and hence are polyclonal)." (PMID 35909553, 2022). "Hashimoto’s thyroiditis (HT) is identified by lymphocytes infiltration in the thyroid gland which leads to the destruction of thyroid follicles, and the production of autoantibodies against thyroid peroxidase (TPO, 90–95%) and thyroglobulin (TG, 20–50%)." (PMID 33114469, 2020). "Although the role of B cells in development of Hashimoto’s thyroiditis is not as significant as in GD, it should be mentioned that they produce autoantibodies to the thyroglobulin (Tg) and thyroid peroxidase (TPO), which are thyroid self-antigens." (PMID 29449887, 2018). "The major autoantigens in Hashimoto’s disease are thyroid peroxidase (TPO) and thyroglobulin (Tg)." (PMID 26062519, 2016). "First, unlike most children with chronic thyroiditis, the only thyroid autoantibodies that have been persistently positive are the anti-thyroglobulin antibodies." (PMID 25114812, 2014). "Diagnosis of Hashimoto's thyroiditis can be made only based on clinical manifestation of hypothyroidism along with high TSHs level as well as some tests on the occurrence of antimicrosomal antibody (AMA) and thyroglobulin antibody." (PMID 24198979, 2013). "The significance of anti-TG in the pathogenesis of Hashimoto’s thyroiditis is not fully understood." (PMID 38999993, 2024).
Hashimoto thyroiditis (continued). "In young patients, preoperative serum thyroglobulin levels and the presence of Hashimoto’s thyroiditis may affect CLNM, while gender is not significantly important." (PMID 35250865, 2022). "Hashimoto’s thyroiditis (HT) is a prevalent autoimmune disorder that primarily impacts the thyroid and is characterized by intrathyroidal monocyte infiltration and elevated serum levels of autoantibodies specific for thyroid peroxidase (TPO-Ab) and thyroglobulin (Tg-Ab)." (PMID 35468730, 2022). "Serum of a Hashimoto thyroiditis patient served as positive control, showing both granular staining in the cytoplasm of the follicle epithelium (white arrowheads) and coarse staining in the colloid of follicles (white asterisk), which represented anti-TPO and anti-TG seropositivity, respectively." (PMID 22126669, 2011). "The different levels of thyroglobulin can be used to evaluate LNM in cases without Hashimoto’s thyroiditis, but not in those with Hashimoto’s thyroiditis." (PMID 40496557, 2025). "Moreover, women comprised a higher proportion of patients with Hashimoto’s thyroiditis than those without, who had lower serum levels of TSH, thyroglobulin, and TPO antibody (p < 0.05)." (PMID 40496557, 2025). "In Pearson’s correlation test, positive correlation was found between lymphocytic thyroiditis and preoperative TSH (r=0.161, p=0.010), anti-TPO (r=0.262, p=0.000), and preoperative anti-TG (r=0.171, p=0.016) values, but negative correlation was found with age (r=–0.152, p=0.015)." (PMID 35317375, 2021).
differentiated thyroid carcinoma (159 papers, 2001 to 2026). Differentiated thyroid carcinoma (DTC), also known as papillary or follicular thyroid carcinoma, is a slow-growing malignancy usually presenting in adults as an asymptomatic thyroid mass. "KS chains have also been detected on transferrin and thyroglobulin in papillary thyroid carcinoma where the KS chains are of diagnostic value." (PMID 38376199, 2024). "Thyroglobulin is the proteogen of thyroid hormones, which is strongly linked to diseases such as differentiated thyroid cancer, subacute thyroiditis, and Graves' disease." (PMID 38022688, 2023). "The presence of anti-Thyroglobulin serum autoantibodies (TgAb) has been reported as an independent risk factor for papillary thyroid carcinoma (PTC), with increase in TgAb prevalence in subjects with PTC and with influence on the prognosis." (PMID 37370937, 2023). "Thyroglobulin measurement in fine-needle aspiration (FNA-Tg) is an additional diagnostic tool of lymph node metastasis (LNM) in papillary thyroid carcinoma (PTC)." (PMID 34386915, 2022). "In this study, we assessed four immunohistochemical markers, CK19, TG, Ki67 and galectin-3, and evaluated their diagnostic significance for papillary thyroid carcinoma in the northeastern region of China." (PMID 22188859, 2011). "Thyroglobulin (Tg) measurement is an essential diagnostic element of the follow‐up and management of patients with differentiated thyroid cancer (DTC), as the 660 kDa glycoprotein is exclusively produced by benign or well‐differentiated malignant thyroid cells." (PMID 35837992, 2022). "A radioiodine-refractory differentiated thyroid cancer patient with rising serum thyroglobulin (Tg) levels underwent 18F-FDG PET/CT scan, which showed a hypermetabolic region in the proximal segment of esophagus, leading to ambiguity in diagnosis." (PMID 41594164, 2026). "Serum thyroglobulin (Tg) serves as the primary marker for follow-up in differentiated thyroid cancers (DTCs)." (PMID 39298113, 2025). "Thyroglobulin (Tg) serves as a pivotal marker in the management of patients with differentiated thyroid cancer (DTC) because of its sensitivity and specificity for detecting residual or recurrent disease, facilitating treatment monitoring." (PMID 39150986, 2025). "Serum thyroglobulin measurements are used in the long-term management of patients with differentiated thyroid cancer following thyroidectomy and radioiodine therapy." (PMID 40532046, 2025). "The patient's last thyroglobulin level was 139 ng/mL, and she died 23 months after the diagnosis of metastatic papillary thyroid carcinoma to the pancreas, which was 13 years after total thyroidectomy for the primary cancer." (PMID 40538612, 2025). "Serum thyroglobulin (Tg) is an established noninvasive biomarker for the detection of differentiated thyroid cancer (DTC) and disease surveillance." (PMID 41551611, 2025). "Postoperative thyroglobulin (Tg) generally serves as a biomarker to monitor the recurrence or persistence of differentiated thyroid cancer (DTC), whereas it constrains to interference from anti-thyroglobulin antibody (TgAb)." (PMID 38721144, 2024). "Thyroglobulin (Tg) is a very sensitive and specific marker in patients who have undergone total thyroidectomy for papillary thyroid carcinoma (PTC)." (PMID 38721086, 2024). "For example, measurement of elevated thyroglobulin (Tg) protein concentration in blood using immunometric assay is an integral part of follow up to monitor residual or recurrence for patients with differentiated thyroid cancer (DTC)." (PMID 38389054, 2024). "The most important part of the follow-up of differentiated thyroid carcinoma (DTC) is the measurement of serum thyroglobulin (Tg)." (PMID 38513355, 2024). "If there is an increase in serum thyroglobulin-antithyroglobulin levels in differentiated thyroid cancer or calcitonin levels in medullary thyroid cancer, patients should be evaluated for recurrence and distant metastasis." (PMID 38344493, 2024).
differentiated thyroid carcinoma (continued). "In papillary thyroid carcinoma (PTC), lower thyroglobulin levels (<30 ng/mL) are associated with significantly higher five-year survival rates (82.1%) and an unachieved median survival, indicating a favorable prognosis (p = 0.012)." (PMID 39767732, 2024). "Two patients with papillary thyroid carcinoma and an elevated thyroglobulin had false-positive imaging studies from intraosseous hemangiomas (IH)." (PMID 37908210, 2023). "The thyroglobulin (Tg)/ thyroid-stimulating hormone (TSH) ratio has manifested to be a reliable marker for predicting prognosis in patients with differentiated thyroid carcinoma (DTC)." (PMID 36670396, 2023). "Thyroglobulin (Tg) is an essential part for the management of patients with differentiated thyroid carcinoma (DTC) after thyroidectomy." (PMID 35837992, 2022). "The neck ultrasound (US) and serum thyroglobulin (Tg) and anti‐Tg antibody (TgAb) assays are the mainstays for Differentiated Thyroid Cancer (DTC) follow‐up." (PMID 35586892, 2022). "Thyroglobulin (Tg) is the most important tumor marker in differentiated thyroid cancer (DTC), and its role in the assessment of the therapeutic response is obvious." (PMID 33467717, 2021). "Fine-needle aspiration cytology (FNAC) with measurement of thyroglobulin concentrations obtained through aspiration (FNA-Tg) is routinely used for the diagnosis of metastatic lymph nodes (LNs) from differentiated thyroid carcinomas." (PMID 33809585, 2021). "Thyroglobulin (Tg) monitoring is the biochemical standard for surveillance of recurrent differentiated thyroid cancer (DTC)." (PMID 34840835, 2021). "Thyrotropin-stimulated thyroglobulin (STg) after total thyroidectomy is a prognosis marker for differentiated thyroid carcinoma (DTC)." (PMID 34283903, 2021). "The presence of CTC compromises serum thyroglobulin (Tg) measurements when the anti-Tg antibody is present in patients with papillary thyroid carcinoma." (PMID 32071283, 2020). "Stimulated thyroglobulin levels measured at the time of remnant ablation (A-hTg) and BRAFV600E mutation had shown prognostic value in predicting persistent disease in differentiated thyroid cancer (DTC)." (PMID 31093278, 2019). "Unexpectedly, papillary thyroid carcinoma metastasis was diagnosed from demonstrative histopathological findings, such as positive immunoperoxidase staining for thyroglobulin." (PMID 31003598, 2019). "Thyroglobulin measurement with fine-needle aspiration (Tg-FNA) is a sensitive method for detecting metastatic papillary thyroid carcinoma (PTC)." (PMID 28454525, 2017). "The most important clinical application of an immunoassay for thyroglobulin is in the follow-up of patients with differentiated thyroid cancer (DTC) which have undergone total thyroidectomy." (PMID 26695140, 2016). "Thyroglobulin is useful to detect residual thyroid tissue after total thyroidectomy and has an important place in the follow-up of patients with differentiated thyroid cancers." (PMID 27029843, 2016). "The 6 papillary CNS metastases had a complete prior workup with IHCs confirming their origin, such as TTF1 and thyroglobulin for papillary thyroid carcinoma, TTF1, CK7, CK20 for lung adenocarcinoma, and Pax8, WT1, CK7, CK20 for serous carcinoma of the ovary." (PMID 27229317, 2016). "The analysis of serum thyroglobulin (Tg) following thyroid-stimulating hormone (TSH) stimulation (sTg) has been recommended in the follow-up of differentiated thyroid carcinoma (DTC) patients, however, its routine use remains controversial." (PMID 25663898, 2015). "The sensitivity of local recurrence detection in differentiated thyroid cancer (DTC) is increased by measuring thyroglobulin in needle washouts from lymph node fine-needle aspiration biopsies (FNA-Tg)." (PMID 25125556, 2014).